PON2 (paraoxonase 2)
Diseases named in the same sentence as PON2 in open-access papers (continued):
Sharing a sentence is not in itself a finding about the gene and the disease.
lung carcinoma (6 papers, 2016 to 2025). "In A549 lung cancer cells, a PON2 deficit resulted in reduced cell death and caspase-3/7 activation upon C12 treatment, while in PON2-deficient cells, actinomycin D and tunicamycin exposure further bolstered cell mortality." (PMID 40794328, 2025). "It was found that PON2 expression deficiency hampered the proliferation of cultured lung cancer cells with concomitant cell cycle arrest at the G1 phase." (PMID 37337025, 2023). "Together, the loss of PON2 expression specifically reduced the proliferation of oncogenically transformed lung epithelial cells, highlighting PON2 as a potentially selective target against lung cancer cell growth." (PMID 37337025, 2023). "Based on previously reported evidence demonstrating PON2 upregulation in lung cancer, further studies were conducted to investigate lung cancer tumorigenesis, both in vitro and in vivo." (PMID 38397445, 2024). "As previously reported, also in lung cancer, PON2 overexpression was found to counteract programmed cell death by balancing ROS production." (PMID 38397445, 2024). "As such, future exploration is warranted to further elucidate the role of PON2 in initiation, progression, and metastasis of lung cancer." (PMID 37337025, 2023). "Here, we conducted studies to investigate how PON2 influences lung cancer cell proliferation in vitro and lung tumorigenesis in vivo using a variety of cellular and animal models." (PMID 37337025, 2023). "Similar to LLC and A549 cells, the lack of PON2 expression in NCI-H1299 cells caused a decrease in cell growth, further validating PON2’s role in regulating lung cancer cell proliferation." (PMID 37337025, 2023). "In the present study, we investigated PON2’s role in lung cancer cell proliferation and lung tumorigenesis." (PMID 37337025, 2023). "Our data also show that PON2 expression is enhanced in lung cancer tissues from NSCLC patients and human bronchia/tracheal epithelial cells transformed by an oncogenic Ras allele." (PMID 26758417, 2016). "It has been shown that PON2 upregulation in some cancer cells, including lung cancer cell lines, enables cancer cells to become resistant to conventional therapeutic drugs." (PMID 26758417, 2016). "Our prior work demonstrated increased PON2 expression in several tumors and established that selected cells undergo spontaneous apoptosis in response to PON2 knockdown, including A549 lung carcinoma cells." (PMID 27322774, 2016). "Among eleven samples from patients, we found that PON2 was overexpressed in eight of lung cancer tissues compared with corresponding adjacent normal tissues, whereas its expression was slightly decreased in three of them." (PMID 26758417, 2016). "Therefore, we investigated how the interplay between PON2 expression in transplanted lung tumors and host mice influences lung cancer progression." (PMID 37337025, 2023). "These considerations may account for the discrepancy between PON2’s role in the proliferation of cultured lung cancer cells and the progression of murine lung tumors." (PMID 37337025, 2023). "Therefore, we conducted studies to investigate how PON2 influences lung cancer cell proliferation in vitro and lung tumorigenesis in vivo using a variety of cellular and animal models." (PMID 37337025, 2023). "Both, human lung carcinomas as well as the SCC4 cell line show high basal PON2 expression." (PMID 27322774, 2016). "To determine whether PON2 expression is enhanced in human lung cancer, we examined PON2 protein levels in tumor tissues of non small cell lung carcinoma (NSCLC) patients by western blot." (PMID 26758417, 2016). "However, the effects of PON2 on lung cancer initiation and progression are unknown." (PMID 37337025, 2023). "Similarly, enhanced intracellular ROS levels were observed as a direct consequence of the lack of PON2 in A549 lung cancer cells." (PMID 40794328, 2025).
pancreatic cancer (6 papers, 2018 to 2021). "In pancreatic cancer cells, PON2 was able to facilitate glucose uptake and increase the efficiency of glucose metabolism by interacting with glucose transporter GLUT1." (PMID 33297311, 2020). "PON2 overexpression controls the cell starvation response and increases glucose uptake to protect pancreatic cancer cells from detachment-induced cell death, which, in part, occurs through suppression of the AMPK/FOXO3A/PUMA signaling pathway." (PMID 31544066, 2019). "Studies have shown that like PON2, PON3 has an oncogenic role and that PON3 is expressed in tumors of the pancreas, lung, bladder, ovary, kidney, and prostate." (PMID 32549522, 2020).
type 2 diabetes (6 papers, 2012 to 2024). "The PON2 G148 variant has been associated with elevated fasting plasma glucose in patients with type 2 diabetes." (PMID 26169365, 2015). "A study conducted on 40 Iranian patients with type 2 diabetes, aged 40–65 years, associated the A allele (SNP PON-2-G148A), and C allele (SNP PON-2-C311S) with quantitative insulin sensitivity check index (QUICKI) and homeostasis model assessment for β-cell function (HOMA-BCF)." (PMID 31052559, 2019). "It is intriguing how from these data collectively an interplay emerges between insulin and glucagon pathways both involved in diabetes type 2, in which PON2 is involved." (PMID 38893310, 2024). "Treatment using herbal medicines or natural compounds that could potentially regulate PON2 might be useful in protecting type 2 diabetes patients with a YZ constitution from cardiovascular complications." (PMID 26169365, 2015).
acute lymphoblastic leukemia (5 papers, 2012 to 2023). Leukemia with an acute onset, characterized by the presence of lymphoblasts in the bone marrow and the peripheral blood. "In a cohort of pediatric and adult patients with B cell acute lymphoblastic leukemia (B-ALL), high PON2 mRNA expression was associated with reduced overall survival and relapse-free survival." (PMID 37337025, 2023). "In a similar manner, our findings match earlier studies in which an upregulation of PON2 was identified in a group of patients who suffered from pediatric acute lymphoblastic leukemia (ALL) with poor outcome prognosis." (PMID 27322774, 2016).
amyotrophic lateral sclerosis (4 papers, 2011 to 2025). Amyotrophic lateral sclerosis (ALS) is a neurodegenerative disease characterized by progressive muscular paralysis reflecting degeneration of motor neurons in the primary motor cortex, corticospinal tracts, brainstem and spinal cord. "Recently, several papers described an association between PON2 C311S and amyotrophic lateral sclerosis (ALS)." (PMID 41303537, 2025). "It is interesting to note that in the last decade several papers associated PON2 and its polymorphisms also with amyotrophic lateral sclerosis (ALS)." (PMID 33562328, 2021).
gastric cancer (4 papers, 2020 to 2025). A primary or metastatic malignant neoplasm involving the stomach. "Others have shown that si-PON2 transfection decreases PON2 levels inside gastric carcinoma cells while increased PON2 mRNA was detected in gastric cancer (GC) tissues, with elevated levels being associated with a reduced likelihood of survival." (PMID 40794328, 2025). "In gastric cancer, elevated PON2 expression correlates with aggressive clinicopathological features such as diffuse tumor type, advanced stages, invasion, and metastasis." (PMID 40794328, 2025). "Induction of PON2 gene silencing in gastric cancer cell lines revealed that enzyme downregulation was associated with a decrease of cell viability, migration, and invasive capacity." (PMID 33297311, 2020).
Hypertension (4 papers, 2012 to 2022). The presence of chronic increased pressure in the systemic arterial system. "Taken together, our results show that the variants of the PON2, ADCY3, PCSK9, and GCKR, together with dyslipidemia, regular intake of eggs and sweets, and hypertension, increased the risk of NAFLD." (PMID 32698306, 2020). "The GG genotype of the additive model of rs7493 in the PON2, the CC genotype of the additive and recessive models of rs7593130 in the ADCY3, together with dyslipidemia, regular intake of egg and sweets and hypertension, increased the risk of NAFLD (adjusted OR > 1, p < 0.05)." (PMID 32698306, 2020).
ischemic stroke (4 papers, 2018 to 2021). A stroke disorder caused by obstruction of blood flow to the brain, due to thrombotic (local blood clot formation) or embolic (due to a blood clot or other material traveling from another site) event. "b) mmu-miR-214-3p/-199b-3p regulated both Pon2 and Qk to inhibit neuronal apoptosis and play a neuroprotective role in the recovery phase of ischemic stroke." (PMID 31681398, 2019).
oral cancer (4 papers, 2020 to 2025). "In oral cancer cell lines, short interfering (siRNA)-mediated PON2 silencing was found to be associated with enhancement of sensitivity to apoptotic damage caused by radiation treatment." (PMID 33297311, 2020). "In order to identify molecular targets for effective oral cancer treatment, we focused on paraoxonase-2 enzyme." (PMID 36613780, 2022). "PON2 silencing in oral cancer cell lines led to a significant reduction of both cell proliferation and viability, to the induction of apoptosis pathway, as well as to a marked enhancement of sensitivity to CDDP treatment." (PMID 36613780, 2022). "Results obtained in this study seem to suggest that PON2 could be somehow involved in mechanisms promoting oral cancer cell resistance to chemotherapy, through the regulation of fundamental processes such as cell proliferation and apoptosis." (PMID 36613780, 2022). "Therefore, paraoxonase-2 gene silencing was achieved in HSC-3 and HOC621 oral cancer cell lines, and the effect on cell proliferation, viability, apoptosis induction and sensitivity to cisplatin and 5-fluorouracil treatment was evaluated." (PMID 36613780, 2022). "Results obtained clearly demonstrated that PON2 expression was significantly (p = 0.001) higher (2.43-fold increase) in cisplatin-resistant compared with parental HOC621 cells, thus highlighting that enzyme upregulation was strictly related to CDDP resistance in oral cancer cells." (PMID 36613780, 2022).
ovarian carcinoma (4 papers, 2018 to 2025). A malignant neoplasm originating from the surface ovarian epithelium. "Elevated PON2 levels have been identified in ovarian cancer phases and metastases, confirming its function as a cancer biomarker." (PMID 40794328, 2025). "PON2 overexpression appears to improve the activity of the mitochondrial electron transport chain and lower the level of superoxides in ovarian cancer cells." (PMID 40794328, 2025). "In this study, elevated PON2 expression blunted ovarian cancer cell proliferation and xenograft tumor growth in mice through inhibiting insulin-like growth factor-1 (IGF-1) expression and signaling transduction." (PMID 37337025, 2023). "It is conceivable that the interaction of lung tumors and microenvironmental factors in our animal studies are distinct from those of PDAC, B-ALL, and ovarian cancer, yielding different impacts of PON2 on tumorigenesis." (PMID 37337025, 2023). "On the other hand, overexpression of PON2 in an ovarian cancer cell line decreased cellular proliferation via the inhibition of IGF-1 expression and signaling." (PMID 37337025, 2023). "In the present study, we analyzed PON2 protein expression by immunohistochemistry using ovarian cancer tissue arrays containing stage I (n = 23), stage II (n = 20), stage III (n = 35), stage IV (n = 12), metastasis (n = 10), and control (n = 20) tissues." (PMID 29531225, 2018). "This present study suggests that PON2 is overexpressed in early stages of ovarian cancer in human subjects and its expression is negatively associated with tumor size and volume in a mouse model." (PMID 29531225, 2018). "Knockdown of PON2 in ID8 cells (mouse ovarian cancer cells) also resulted in increased IGF-1 expression like that observed in SKOV3 cells (data not shown)." (PMID 29531225, 2018). "Utilizing molecular, biochemical, and immunological approaches, we demonstrate that PON2 decreases ovarian cancer cell proliferation by regulating both IGF-1 expression as well as IGF-1 signaling." (PMID 29531225, 2018). "Why PON2 is differentially regulated at various stages of ovarian cancer and what is its role in ovarian tumor formation?" (PMID 29531225, 2018). "How does PON2 reduce IGF-1 signaling in ovarian cancer cells?" (PMID 29531225, 2018). "Although currently it is unknown why PON2 was downregulated in late stages of ovarian cancer compared to early stages within the ovary and in lymph node where it was increased." (PMID 29531225, 2018). "Hence, instead of directly targeting IGF-1/IGF-1R, which has adverse effect on glucose hemostasis, activating PON2 would be a fruitful alternative strategy for treating ovarian cancer." (PMID 29531225, 2018). "PON-2, an antioxidant protein, has a protective role in ER stress from apoptosis, and overexpression of PON-2 inhibits tumor development by inhibiting insulin-like growth factor-1 (IGF-1) expression and signaling in ovarian cancer cells." (PMID 33182770, 2020). "How does PON2 reduce IGF-1 levels and cell proliferation in ovarian cancer cell lines?" (PMID 29531225, 2018).
asthma (3 papers, 2014 to 2024). "The first is an epidemiologic study showing that a polymorphism in PON2 was associated with increased asthma incidence." (PMID 39594475, 2024). "We also found for the first time genetic polymorphisms of the GSR and PON2 genes can be important determinants of susceptibility to asthma, but their associations need to be confirmed in independent populations." (PMID 24895604, 2014). "We identified GSR (glutathione reductase) and PON2 (paraoxonase 2) as novel candidate genes for asthma susceptibility." (PMID 24895604, 2014). "In particular, we found for the first time that the GSR and PON2 genes can be referred to as novel asthma susceptibility genes, but their associations need to be confirmed in independent populations." (PMID 24895604, 2014). "Because airway epithelial mitochondrial dysfunction has been linked to the pathogenesis of asthma and PON2 is localized to the inner mitochondrial membrane, we hypothesized that decreased PON2 production would impact airway epithelial mitochondrial function." (PMID 39594475, 2024). "Two prior studies have investigated the effect of PON2 in airway physiology, both focused on asthma." (PMID 39594475, 2024). "Further studies are needed to elucidate the mechanisms linking PON2, oxidant stress, and asthma pathogenesis." (PMID 39594475, 2024). "Our findings suggest that efforts to boost mitochondrial antioxidant defense and PON2 expression in patients with T2-low asthma may be beneficial and are worthy of further research." (PMID 39594475, 2024). "While the IL5 and PON2 genes showed an association only with allergic asthma, none of the studied genetic polymorphisms was found to be associated exclusively with the risk of nonallergic asthma." (PMID 24895604, 2014). "Our work expands on these findings by demonstrating that decreased expression of Pon2 leads to worsened in vivo oxidant-induced AHR in mice, which is a defining physiologic feature of asthma." (PMID 39594475, 2024).
depression (3 papers, 2022 to 2023). "mRNA expression of the PON1, PON2 and PON3 genes was slightly higher in patients with depressive disorders than in the control group, however, this relationship was not statistically significant." (PMID 35743392, 2022). "mRNA expression of PON1, PON2 and PON3 genes was slightly higher in patients with depressive disorders than in the control group, however this relationship was not statistically significant (PON1 p = 0.5895, PON2 p = 0.1342 and PON3 p = 0.2818)." (PMID 35743392, 2022).
diabetic nephropathy (3 papers, 2018 to 2023). "The PON2 gene polymorphisms A148G and S311C have been independently linked to diabetic nephropathy in type II diabetic patients." (PMID 37891899, 2023). "Accordingly, the PON2 variants A184G and S311C are associated with diabetic nephropathy in patients with type II diabetes and obesity." (PMID 36429053, 2022). "One previous meta-analysis assessed the association of PON2 Ser311Cys and Ala148Gly gene polymorphisms with diabetic nephropathy and retinopathy in Caucasian populations." (PMID 30210454, 2018). "We stained for PON2 on the kidney samples from patients with proteinuric kidney diseases such as minimal change nephropathy (MCN), early-stage diabetic nephropathy, and systemic inflammatory diseases such as systemic lupus erythematodes (SLE) and ANCA-associated vasculitis (AAV)." (PMID 36429053, 2022).
glioma (3 papers, 2019 to 2021). A benign or malignant brain and spinal cord tumor that arises from glial cells (astrocytes, oligodendrocytes, ependymal cells). "The relative expression of LOC441179 and PON2 in glioma cells was significantly higher than in control cells (P < 0.05)." (PMID 30984542, 2019). "The glioma cell line GBM expressed a higher PON2 protein level compared with normal brain tissue, providing support for the importance of PON2 for cancer cell survival." (PMID 30984542, 2019). "qRT‐PCR was performed to investigate the expression of LOC441179, PON2 and USP46‐AS1 in glioma cells compared to control cells." (PMID 30984542, 2019). "Survival rate is an important indicator of prognosis after treatment, and the significant association of survival rate with the expression levels of USP46‐AS1, PON2 and LOC441179 suggests that those three ncRNAs should be important indicators for prognosis prediction for glioma patients." (PMID 30984542, 2019). "Besides this, random survival forest analysis identified a prognostic signature that is the weighted composition of expression values of three ncRNAs, namely LOC441179, PON2 and USP46‐AS1, that could accurately separate glioma samples with longer OS from those with shorter OS." (PMID 30984542, 2019).
Hypercholesterolemia (3 papers, 2019 to 2025). An increased concentration of cholesterol in the blood. "In the future, the detailed mechanistic understanding of PON2’s effects on ASGR1, coupled with the in vivo evidence of its therapeutic potential, may open up new possibilities for the development of targeted therapies for metabolic diseases, particularly hypercholesterolemia." (PMID 39055948, 2024).